PAX8 (paired box 8)
Diseases named in the same sentence as PAX8 in open-access papers (continued):
Sharing a sentence is not in itself a finding about the gene and the disease.
tumor (continued). "We also performed PAX8 immunohistochemical stain to identify if there is a possible evidence of Müllerian differentiation in the tumor." (PMID 23044077, 2012). "Moreover, IHC staining for PAX8 revealed a decrease in the percentage of viable tumor cells after treatment, in all but one specimen." (PMID 40410344, 2025). "In contrast, while similar studies performed on the liver metastasis also showed that the tumor cells expressed PAX8, the percentage of cells expressing other renal markers was markedly higher than in the brain lesion with CA9 expression measured at 77.0% and CD10 expression at 29.5%." (PMID 39833894, 2025). "PAX8 staining revealed comparable cancer cell viability between Fresh and SF cultures, which was accompanied by only a marginal difference in tumor coagulative necrosis, implying effective tumor preservation under both culture conditions." (PMID 40410344, 2025). "Since in the ascites this mutation was present at low VAF (3.14%), we could ascertain its tumor specific nature and confirm cancer cells were indeed present in the ascites despite the inconclusive PAX8 staining." (PMID 40051502, 2025). "The percentage of PAX8+ cells in the tumor mass was higher in perfused culture, when compared to the static counterpart (p = 0.03), highlighting the advantages of perfusion in maintaining tumor histological morphology and antigenicity." (PMID 40410344, 2025). "PAX8::PPARG is primarily associated with follicular-pattern thyroid carcinomas, found in approximately one third of adult FTCs and fvPTCs, and is associated with more extensive capsular and vascular invasion compared to RAS-positive tumours." (PMID 40361475, 2025). "This tumor is usually positive for Pax8, melanocytic markers (melan-A and HBM-45), and cathepsin-K." (PMID 39502747, 2024). "Moreover, PAX8 is a specific marker for these tumors, suggesting an important role in tumor development." (PMID 39592661, 2024). "Some case reports revealed positive PAX8 in immunohistochemistry of the tumor cells." (PMID 38835742, 2024). "Although neoplasms derived from kidney, thyroid, and the female genital tract were most often and most strongly PAX8 positive, there were 15 additional tumor types exhibiting PAX8 positivity at least in occasional cases." (PMID 39105782, 2024). "The treatment-naive tumor organoids were developed exclusively from the cancer cells of the treatment-naïve patient samples (Online “Methods”), which displayed an elevated expression of PAX8." (PMID 39362905, 2024). "Immunohistochemical analysis revealed strong positive expression of CAM52 and Pax-8 in tumor cells." (PMID 38903727, 2024). "In addition to typical HE staining, spheroids were also immunohistological stained with PAX8 as a tumour marker and FAP as a fibroblast marker." (PMID 39384844, 2024). "PAX8 may mediate some tumour-promoting effects through FOXM1 and tumour invasiveness through upregulation of FGF18." (PMID 36804485, 2023). "Transcription factor PAX8 is critical in the formation of tissues and organs during embryonic development, but it also promotes the proliferation and survival of tumour cells when its expression is increased." (PMID 36695960, 2023). "This revealed that MECOM, PAX8, SOX17 and WT1 are lineage-enriched, super-enhancer associated master regulators whose cooperative DNA-binding patterns and target genes are re-wired during tumor development." (PMID 37090516, 2023). "Antitumor activity of CD3-T-cell-binding bispecific antibodies (TCBs) directed against the PAX8 lineage-driven HGSOC tumor antigen LYPD1 showed that anti-LYPD1 TCBs induce T cell activation and in vivo promote inhibition of tumor growth in LYPD1-expressing HGSOC." (PMID 38001616, 2023). "GATA binding protein 3 (GATA3), E-cadherin and Pax-8 were also present in all neoplasms." (PMID 36816543, 2023).
tumor (continued). "PAX8 can promote invasion and tumor cell migration through modulating FOXM1 and PKCα expression." (PMID 37891636, 2023). "Some epithelial markers (CK(pan), CK7, EMA, and PAX8) were expressed in the tumor." (PMID 38097964, 2023). "In all cases tested, the tumor cells were positive for PAX8 (2/2, diffusely in both), GATA3 (4/4, diffusely in two and focally in two), and TTF1 (3/3, focally in two and diffusely in one), and the one (case 3) which was diffusely positive for TTF1 also diffusely expressed GATA3." (PMID 35865471, 2022). "PAX8 has been used for a long time as a marker to distinguish whether it is derived from the female reproductive system, but its role in tumor progression seems to have been neglected." (PMID 35672291, 2022). "However, PAX8 can be expressed in both ccRCC and CCOC, which makes it difficult to determine the primary site of the tumor by PAX8 positivity." (PMID 33608777, 2021). "We investigated the anti-tumor activity of CD3 T cell engaging bispecific antibodies (TCBs) directed against the PAX8 lineage-driven HGSOC tumor antigen LYPD1 and demonstrated that anti-LYPD1 TCBs induce T cell activation and promote in vivo tumor growth inhibition in LYPD1-expressing HGSOC." (PMID 34290299, 2021). "We found a statically significant relationship between PAX8 expression and tumor size (P=0.033)." (PMID 34306127, 2021). "Herein, we described the preclinical efficacy and non-human primate toxicology profile of the monovalent high-affinity and bivalent low-affinity anti-LYPD1 TCBs that selectively target tumor cells expressing the PAX8 lineage-driven cell surface antigen LYPD1 in HGSOC." (PMID 34290299, 2021). "PAX-8 expression is detected in the primary tumor and distant sites." (PMID 33809250, 2021). "We present a series of 15 cases of molecularly confirmed ES, trying to find the meaning of its immunoreactivity for CD99 and PAX8, to determine whether there is enough sensitivity to be useful in the diagnosis of these tumours." (PMID 32675940, 2020). "Our results build upon this knowledge, allowing to assign PAX8 as a FI-like HGSOC-specific target that could be investigated for improved treatment of this tumor subtype." (PMID 33121525, 2020). "The histological examination and PAX-8 immunostaining of multiple biopsies from the tumor or lymph nodes may be useful in the confirmation of this diagnosis." (PMID 32748087, 2020). "Interestingly, 74, which yielded a PAX8-negative OCM 9 years later, displayed focal PAX8 staining indicating that heterogeneity already existed in the primary tumour." (PMID 32054838, 2020). "Increasing evidence indicates that PAX8 plays important roles in tumor development." (PMID 31915309, 2020). "PAX8, encoding a transcription factor of the paired box (PAX) family, has been predicted to be a potential identification marker for the distinction of different tumor tissues in PDX mouse models." (PMID 31456818, 2019). "PAX-8 expression confirmed that the tumor cells were of ovarian origin." (PMID 31619730, 2019). "Either of the treatments efficiently eradicated PAX8 protein as well as PAX8-positive tumor cells." (PMID 31050342, 2019). "If the tumor is positive for PAX8, it is most likely to be of ovarian origin." (PMID 31771640, 2019). "Taken together, these findings suggest PAX8 could be targeted for drug development to reduce proliferation, migration and survival of tumor cells while leaving other organs unaffected." (PMID 30096791, 2018). "The concept of a biological continuum in tumor progression starting from FA evolving to FTC is supported by two strong arguments: firstly, the common predominant mutations encountered in FA and FTC, i.e. RAS mutations and PAX8-PPARγ rearrangements." (PMID 29535811, 2018).
tumor (continued). "Molecules that increase expression of PAX2 may also increase expression of PAX8, which could then increase the aggressive properties of a tumor cell." (PMID 30096791, 2018). "We identified somatic mutations in NBN, p.P6S, and PAX8, p.R49H, in the LN metastasis; however, we did not identify these mutations in the primary tumor." (PMID 29535844, 2018). "It is possible that PAX8 knockdown reduces the level of cellular adhesion, which may explain the reduced tumor burden in HeyA8 xenograft mice." (PMID 29312534, 2017). "Consistent with a renal epithelial phenotype, scattered cells in allograft tumours derived from total sphere populations or from sphere clonal cell lines expressed the transcription factor PAX8, which is normally expressed in epithelia of the renal and genital-urinary tract." (PMID 29133867, 2017). "Highest PAX8 expression was associated with advanced stage carcinomas, compared to low stage carcinomas (p = 0.013), but did not correlate with tumor grade." (PMID 29312534, 2017). "PAX8 is overexpressed in many reproductive tract cancers and it is currently unclear if it has the same or different functions in these tumor types, and what the variation may be between patients." (PMID 29312534, 2017). "Even in the absence of a PAX8 inhibitor, inhibiting these cofactors may be sufficient to inactivate oncogenic PAX8 signaling and impair tumor growth." (PMID 29312534, 2017). "Paired box transcription factor 8 (PAX8) may provide clues regarding a tumor's cell of origin due to its differential expression in the FTE, OSE, and HGSC." (PMID 27129161, 2016). "PAX8, a marker for renal differentiation, was also positive diffusely in the tumor nuclei." (PMID 26337721, 2015). "Most remarkable is the presence of classic cancer hallmark GO terms in the WT1-wild-type tumour/Pax8+/CreWt1 conditional sets but absence of these in the Nes-Cre-driven mutants/WT1-mutant tumours." (PMID 26035382, 2015). "Using genomic DNA extracts prepared from NSCLC archival tumor tissues, we failed to see any mutations in PAX8 genomic DNA (exons), while MET mutations were apparent (data not shown)." (PMID 24628993, 2014). "In summary, all tumours typed as PAX8-positive by IHC were verified as PAX8-positive by QPCR." (PMID 24602166, 2014). "Having previously established that PAX8 enhances motility, invasion and tumor formation, we hypothesized that it could also play a role in epithelial-mesenchymal transition (EMT)." (PMID 24766781, 2014). "A small number of the low-grade tumours were PAX8-positive (6%)." (PMID 24602166, 2014). "Due to diagnostic challenges—germ cell phenotype, SALL4 positivity, weak PAX8 positivity suggesting mediastinal germ cell carcinoma, while clinical features argued for a poorly differentiated epithelial thoracic malignancy—the case was presented to the tumor board for further evaluation." (PMID 40421964, 2025). "Furthermore, miR-323b negatively regulates paired-box 8 (Pax8), a transcription factor essential for embryo development, central nervous system, angiogenesis, immune regulation, and tumor metastasis as well as for the regulation of cell proliferation and differentiation." (PMID 41417751, 2025). "Interestingly, the same sample retained a higher number of PAX8+ tumor cells, showed a reduced extent of tumor necrosis, and exhibited a comparable mitotic index to the corresponding UT, indicating a potential degree of resistance following treatment in this sample." (PMID 40410344, 2025). "In addition, interspersed normal follicular cells which are commonly seen between tumor cell layers may have contributed to the perception of PAX8 positivity in medullary cancers." (PMID 39105782, 2024).
tumor (continued). "In addition, the tumor growth pattern and the PAX8 immunophenotype might represent potential prognostic biomarkers for PMOC." (PMID 37664708, 2023). "Likewise, ATF2, CHEK1, DCAF8, and PAX8 showed diverse expression across the different tumor grades." (PMID 36831395, 2023). "Hence, PAX8 overexpression in tumor cells promotes aggressive tumor behavior." (PMID 36140438, 2022). "The diagnosis of anaplastic papillary thyroid cancer could only be made with the detection of PAX-8 expression in a highly atypical lesion of the tumor located in the mesentery tissue as well as with the finding of the squamous differentiation of metastatic lymph node cells." (PMID 32748087, 2020). "It is imperative to further explore this particular function of PAX8 in altering the interaction of HGSC cells with their tumor microenvironment as this transcription factor could possibly have more than one mechanism and this could be critical in improving the current therapeutic regimen." (PMID 31832016, 2019). "In conclusion, taking PAX8 as an example, we present the proof-of-concept research that integrates bioinformatics-assisted, screen-guided and mechanism-driven approaches to tackle the critical challenge of understanding and targeting lineage-survival oncogenes in often difficult-to-treat neoplasms." (PMID 31050342, 2019). "Thus, studying the shared regulatory mechanisms of PAX2 and PAX8 expression between the fallopian tube and ovary will be essential to developing effective treatment therapies until the site of origin of a patient’s tumor can be definitively identified." (PMID 30096791, 2018). "Finally, we determined the effect of PAX8 overexpression on tumor metastasis in vivo." (PMID 30021604, 2018). "In concordance with the observed luminescence signals, palpable tumors could be resected in control mice, whereas only microscopic tumor cells that stained positive for PAX8 were detectable by immunohistochemistry in all of the four mice inoculated with cells expressing inducible shGAB2." (PMID 26657155, 2016). "Diffuse expression of PAX8 in the tumor might present with a renal origin." (PMID 26337721, 2015). "PAX8 transactivates the promoters of the telomerase catalytic subunit (hTERT) and the telomerase RNA component (hTR) to increase telomerase activity, and as might be predicted, the majority of the telomerase-positive tumours were also PAX8-positive." (PMID 24602166, 2014). "Finally, our results for individual variants in TSHR and possibly TG, and the epistatic effect of the SNPs in PAX8 and STK17B, all apparently stronger for specific disease subtypes, stress the potential importance of tumor characterisation and stratification in association studies." (PMID 24086368, 2013). "Our findings indicate that PAX8 negatively regulates CCDC80, a novel cell autonomous tumor suppressor in HGSC." (PMID 42011738, 2026). "Immunohistochemistry is vital for establishing the diagnosis of LOT, as evidenced by tumor cell positivity for CK7 and PAX8 and negativity for CD117/KIT, vimentin, and CAIX." (PMID 41523983, 2026). "Western blot analysis of tumor lysates from M02 was positive for WT1 expression, while M10 showed Pax8 and WT1 positivity, consistent with immunohistochemistry analysis from both patients’ original specimen." (PMID 41413213, 2025). "This was consistent with clinical observations, such as higher rates of RAI-resistance in BRAF-positive tumours and follicular architecture in RAS- and PAX8::PPARG-positive tumours." (PMID 40361475, 2025). "The follicular areas of the tumor were positive for thyroglobulin, thyroperoxidase, TTF1, and PAX8, supporting a follicular lineage, while the meaning of the morular structures is intriguing." (PMID 40892116, 2025).
tumor (continued). "To assess the fidelity of our patient-derived organoids, we compared the expression and spatial distribution of key tumor markers (EpCAM, PAX8, and CA125) between organoids and their original tumor tissues." (PMID 41009433, 2025). "When we checked the expression of PAX8 in the two generations of PDCX and PDTX tumor tissues, it was well preserved, the same as in the original primary tumors." (PMID 40072054, 2025). "Tumor cells in angiomatoid ATC display epithelial markers (cytokeratins, EMA), and occasionally stain with endothelial markers as well as PAX8, TTF1, and podoplanin." (PMID 40214777, 2025). "PAX8 and EMA, reliable markers of epithelial cell origin and are therefore specific to the carcinoma portion of the tumor." (PMID 40027125, 2025). "The HMucBOT-1 tumor expressed the epithelial markers CK7, PAX8, and MUC1 in the borderline lesions; in addition, these markers were expressed in cell lines." (PMID 40427213, 2025). "In our case, the tumor exhibited positive staining for CK5/6, P40, P63, and CK7, while showing negative staining for Napsin A, TTF-1, CD56, Chromogranin A, Synaptophysin, Pax-8, thyroglobulin, and vimentin." (PMID 40061900, 2025). "Immunohistochemical stains (IHC) showed the tumor positive for cytokeratin 7 (CK7) and CK 19, and weakly positive for paired box gene 8 (PAX8)." (PMID 40182334, 2025). "In our patient, the histology analysis revealed a favorable histology made of a triphasic tumor, and immunohistochemistry showed positivity for WT1 and PAX8." (PMID 39844890, 2025). "HBx also affects the degradation of cell cycle‐related proteins such as paired box 8 (PAX8) and pituitary tumor‐transforming gene 1 (PTTG1), disrupting normal cell cycle control and extending proliferation signals, promoting a tumor microenvironment." (PMID 40060195, 2025). "The tumor cells exhibited positivity for cytokeratin 7 (CK7) and caudal type homeobox 2 (CDX-2) but negativity for cytokeratin 20 (CK20), paired box 8 (PAX8), NK3 homeobox 1 (NKX3.1), and thyroid transcription factor 1 (TTF-1)." (PMID 39350874, 2024). "Results of IHC on CD10, CK7 and TFE3 were concordant among parental tumor tissues, organoids and ODX, while PAX8 and CA‐IX expressions were specific to organoid and ODX only." (PMID 38923304, 2024). "Immunohistochemistry revealed that the tumor cells were positive forcytokeratin AE1/AE3, hepatocyte nuclear factor-1-beta (HNF1β) and PAX8 andnegative for thyroglobulin and thyroid transcription factor-1 (TTF-1)." (PMID 39700333, 2024). "Immunohistochemical staining demonstrated that the tumor cells were positive for vimentin, CD10, PAX8, and CA‐IX." (PMID 39031907, 2024). "In terms of immunohistochemical (IHC) staining, most tumor cells have been shown to stain positive for Vimentin, CD10, PAX8, and AMACR." (PMID 39234013, 2024). "Immunohistochemistry stains showed the tumor was positive for synaptophysin, chromogranin, INSM1, AE1/AE3, PAX8 (MRQ-50 clone), CDX2 (patchy, weak), MOC31, and CD10 and was negative for claudin-4, CK7, CK20, GATA3, TTF1, p40, and S100; Ki-67 index was 1.5 %." (PMID 39561576, 2024). "Immunohistochemistry revealed that the tumor cells were positivefor cytokeratin AE1/AE3, hepatocyte nuclear factor-1-beta and PAX8 andnegative for thyroglobulin and thyroid transcription factor-1." (PMID 39700333, 2024).